PTPN2 (protein tyrosine phosphatase non-receptor type 2)
Diseases named in the same sentence as PTPN2 in open-access papers (continued):
Sharing a sentence is not in itself a finding about the gene and the disease.
Lymphadenopathy (6 papers, 2012 to 2025). Enlargement (swelling) of a lymph node. "We report on a 32-year-old male patient with interstitial lung disease, cytopenia, and lymphadenopathy accompanied by de-novo deletion in PTPN2." (PMID 39959585, 2025). "A strong evidence for the role of PTPN2 in the inflammatory process is that PTPN2 knockout mice develop severe inflammation with splenomegaly, lymphadenopathy and excessive production of TNF-α, IFN-γ, IL-12 and nitric oxide, then die 5 weeks after birth." (PMID 27611995, 2016). "Ptpn2−/− (BALB/c-129SJ) mice develop thymic atrophy associated with a drop in double positive (CD4+CD8+) thymocytes, lymphadenopathy and splenomegaly, the latter being associated with an accumulation of myeloid cells and the sequestration of red blood cells." (PMID 22590589, 2012). "Lymphadenopathy and increases in lymph node (LN) cellularities have also been reported for Ptpn2−/− (BALB/c-129SJ) mice." (PMID 22590589, 2012).
Splenomegaly (6 papers, 2012 to 2025). Abnormal increased size of the spleen. "In addition to thymic atrophy Ptpn2−/− (BALB/c-129SJ) mice develop splenomegaly after two weeks of age." (PMID 22590589, 2012). "Ptpn2ex2−/ex2− mice had defects in erythropoiesis and B cell development as evident in Ptpn2−/− (BALB/c) mice, but not splenomegaly and did not exhibit an accumulation of myeloid cells in the spleen as seen in Ptpn2−/− (BALB/c) mice." (PMID 22590589, 2012).
acute lymphoblastic leukemia (5 papers, 2021 to 2025). Leukemia with an acute onset, characterized by the presence of lymphoblasts in the bone marrow and the peripheral blood. "In contrast, PTPN2 is likely a tumor suppressor in acute lymphoblastic leukemia (ALL) because it inhibits JAK1, which is oncogenic in ALL, though PTPN2 levels are often low in ALL." (PMID 35911672, 2022).
Hyperglycemia (5 papers, 2016 to 2025). An increased concentration of glucose in the blood. "The fasting blood glucose level also showed that PTPN2 overexpression improved hyperglycaemia in T2DM mice." (PMID 37251330, 2023). "PTPN2 gene therapy markedly improved frank hyperglycaemia, glucose tolerance and IR, indicating that better blood glucose control in diabetic mice by PTPN2 overexpression." (PMID 30955247, 2019). "Based on this research, we found the PTPN2 expression in the gingival epithelium negatively correlated with the severity of periodontal destruction and hyperglycemia." (PMID 27995146, 2016). "PTPN2 gene therapy markedly attenuated metabolic disorders and hyperglycaemia." (PMID 30955247, 2019). "The biological function of PTPN2 is believed to vary in response to proinflammatory stimuli such as interferon-gamma (IFN-γ), tumor necrosis factor (TNF-α), hyperosmotic stress, or hyperglycemia." (PMID 27995146, 2016). "Notably, PTPN2 treatment significantly decrease serum TG, total cholesterol, and LDL levels, as well as reducing metabolic disturbances and hyperglycemia in mice." (PMID 41019340, 2025). "It has been universally recognized that simply targeting systemic hyperglycaemia and metabolic disorders is not sufficient to arrest the progression of DN, indicating that there must be other molecular mechanism responsible for therapeutic effects of PTPN2 for DN." (PMID 30955247, 2019).
Immunodeficiency (5 papers, 2022 to 2025). Failure of the immune system to protect the body adequately from infection, due to the absence or insufficiency of some component process or substance. "PTPN2 is associated with pathological processes, including inflammatory responses, immune disorders, and tumor development." (PMID 36077422, 2022).
pancreatic adenocarcinoma (5 papers, 2020 to 2025). "Consistently, analysis of the TCGA database demonstrates that high expression of PTPN2 is significantly associated with poor prognosis of patients with KRAS-mutant pancreatic adenocarcinoma." (PMID 33122197, 2020). "However, PTPN2 is a key predictor of prognosis for pancreatic adenocarcinoma, and its higher expression is associated with a poor prognosis." (PMID 37509645, 2023). "Importantly, increased PTPN2 expression was linked to poor prognosis in pancreatic adenocarcinoma (PAAD)." (PMID 38022587, 2023). "For example, PTPN2, known for its anti-inflammatory properties, emerges as a potential therapeutic target for both RA and pancreatic adenocarcinoma (PAAD) due to its ability to moderate inflammation and reduce tumor malignancy." (PMID 40839671, 2025).
prostate carcinoma (5 papers, 2016 to 2023). A carcinoma that arises from epithelial cells of the prostate gland. "To conclude, PTPN2 might be a potential target in prostate cancer treatment, whose targeting is achievable because the PTPN2 inhibitors are available." (PMID 37509645, 2023). "However, the potential role of PTPN2 activation by integrins in prostate cancer remains to be investigated." (PMID 37509645, 2023). "While PTPN1 and PTPN12 were implicated in prostate cancer biology, the involvement of PTPN2 in prostate cancer is not documented." (PMID 37509645, 2023). "To conclude, by using the Gleason score information supplemented with the expression of FMOD and PTPN2 genes, a stratification of prostate cancer patients into several prognostic subgroups with significantly different hazard ratios (low, medium, and high risk of progression) was achieved." (PMID 37509645, 2023). "PTPN1 and PTPN2 are highly related PTPs, but PTPN2 has not been implicated in prostate cancer." (PMID 37509645, 2023). "The expression of genes that we showed are involved in the prognosis of PFS of prostate cancer patients, PTPN2 and FMOD, did not change the global expression between prostate cancer and non-transformed tissue according to the criteria used (|log2FC| ≥ 1 and FDR p-value < 0.01)." (PMID 37509645, 2023).
anaplastic large cell lymphoma (4 papers, 2021 to 2025). Anaplastic large cell lymphoma (ALCL) is a rare and aggressive peripheral T-cell non-Hodgkin lymphoma, belonging to the group of CD30-positive lymphoproliferative disorders, which affects lymph nodes and extranodal sites. "Studies have shown that PTPN1 and PTPN2 deficiency in anaplastic large cell lymphoma (ALCL) leads to ALK-TKI resistance in ALCL." (PMID 36115852, 2022). "Furthermore, loss of PTPN1 and PTPN2 expression was recently identified as an important driver of anaplastic large cell lymphoma (ALCL) resistance to anaplastic lymphoma kinase (ALK) inhibitors." (PMID 38334623, 2024). "In addition, PTPN1 and PTPN2 have been shown to dephosphorylate ALK and PTPN11 in anaplastic large cell lymphomas, and gene deletion of either PTPN1 or PTPN2 induced resistance to ALK inhibitors." (PMID 34957126, 2021).
atherosclerosis (4 papers, 2020 to 2023). A disease characterized by the build-up of fatty material and calcium deposition in the arterial wall resulting in partial or complete occlusion of the arterial lumen. "Answers to such questions will undoubtedly provide unique insights into the role of PTPN2 in atherosclerosis and make PTPN2 an attractive therapeutic target aiming at reducing atherosclerosis." (PMID 37670950, 2023). "In this review, we summarize the latest findings on the role of PTPN2 in the pathogenesis of atherosclerosis to provide a rationale for better future research and therapeutic interventions." (PMID 37670950, 2023). "Studies have shown that the expression of PTPN2 in monocytes is significantly downregulated in the apoE−/− inflammatory mouse atherosclerosis model." (PMID 37670950, 2023). "These current studies demonstrate that PTPN2 in macrophages inhibits the development of atherosclerosis by regulating IFN-γ, JAK/STAT1, IL-4/6, and NF-κB-induced inflammation." (PMID 37670950, 2023). "PTPN2 mainly inhibits the occurrence and development of atherosclerosis by negatively regulating the expression of downstream target genes and their signaling pathways." (PMID 37670950, 2023). "PTPN2 assists in inhibiting the release of inflammatory factors in macrophages via de-phosphorylating p65/p38/STAT3 in an atherosclerosis model." (PMID 36077422, 2022). "To explore the potential application value of PTPN2 on the treatment of atherosclerosis, we performed an in vivo assay in APOE-/- mice." (PMID 33411686, 2020). "In order to reveal the function of PTPN2 in the occurrence of atherosclerosis, we artificially synthesized two shRNA of PTPN2 gene, and used the THP-1 cell and U937 cell as the model to research." (PMID 33411686, 2020). "We constructed an APOE-/- mice model of atherosclerosis, and found that PTPN2 was dramatically decreased in inflammatory mice." (PMID 33411686, 2020). "Therefore, further studies of PTPN2 are required to clarify its exact role in atherosclerosis in the future." (PMID 37670950, 2023). "Therefore, it can be found that PTPN2 inhibits the development of atherosclerosis by regulating the autophagy of macrophages." (PMID 37670950, 2023). "PTPN2 inhibits the development of atherosclerosis by inhibiting pyroptosis and thus may serve as a potential regulatory target of atherosclerosis." (PMID 37670950, 2023). "In addition, several key questions remain to be answered in future studies: 1) Are there other target genes of PTPN2 that can influence the progression of atherosclerosis?" (PMID 37670950, 2023). "Multiple studies have found that PTPN2 may inhibit atherosclerosis through the following mechanisms." (PMID 37670950, 2023). "PTPN2 has a significant anti-inflammatory effect, which can inhibit or reduce the occurrence of inflammation by regulating related signaling pathways, and then reduce the occurrence and development of atherosclerosis." (PMID 37670950, 2023). "In vivo experiments showed that PTPN2 may effectively inhibit the inflammatory response during atherosclerosis." (PMID 33411686, 2020). "Therefore, PTPN2 may serve as an important target for regulating T cell polarization, thereby protecting atherosclerosis." (PMID 37670950, 2023). "Therefore, PTPN2 may act as a regulatory target of atherosclerosis and exert an anti-atherosclerotic effect." (PMID 37670950, 2023). "Therefore, I speculate that PTPN2 may inhibit the progression of atherosclerosis by regulating lipid metabolism in macrophages, but this requires further investigation in the future." (PMID 37670950, 2023). "In vivo experiments showed that PTPN2 could inhibit the inflammatory response in atherosclerosis." (PMID 33411686, 2020). "Therefore, we analyzed the expression of PTPN2 in APOE-/- mice model of atherosclerosis." (PMID 33411686, 2020). "In conclusion, we uncovered the negative role of PTPN2 in the occurrence of atherosclerosis, and this study provides a new potential target for atherosclerosis treatment." (PMID 33411686, 2020).
atherosclerosis (continued). "The results indicate that PTPN2 plays a negative role in the occurrence of atherosclerosis by inhibiting the secretion of inflammatory factors in macrophages and may be a treatment candidate for atherosclerosis." (PMID 36077422, 2022). "We uncovered the negative role of PTPN2 in macrophages inflammation, and this work may provide a new potential target for atherosclerosis treatment." (PMID 33411686, 2020). "In a word, in vitro and in vivo results suggested that PTPN2 has a negative role on the regulation of macrophage inflammation in atherosclerosis, and it may become a potential target for atherosclerosis treatment." (PMID 33411686, 2020). "These works suggested that PTPN2 plays an anti-inflammatory role in the occurrence of atherosclerosis, and the absence of PTPN2 may lead to the persistent inflammation in macrophages." (PMID 33411686, 2020).
B-cell lymphoma (4 papers, 2019 to 2025). "PTPN2 played tumor-promoting functions in B-cell lymphomas, and Ptpn2 depletion decreased murine B-cell lymphoma cell proliferation and completely abolished the cancer in vivo." (PMID 33122197, 2020). "We repeated NK-92 competitive co-culture experiments after disruption of DCAF15, PTPN2, STAT1 and ICAM1 in Daudi cells, a B2M-deficient B-cell lymphoma line." (PMID 31452512, 2019). "Moreover, PTPN2 is a pro-tumor gene in MYC-driven B-cell lymphoma, and contributes to tumor proliferation by promoting G1 to S phase transition of the cell cycle." (PMID 36077422, 2022).
ovarian carcinoma (4 papers, 2017 to 2022). A malignant neoplasm originating from the surface ovarian epithelium. "Analyzing ovarian cancer-related genes using the Cancer Genome Atlas (TCGA) and Gene Expression Ominbus (GEO) datasets identified PTPN2 as one of the protective genes for ovarian cancer." (PMID 36077422, 2022). "The abnormal expression of PTPN2 is highly related to ovarian cancer progression, and can be used as an independent prognostic marker of ovarian cancer." (PMID 36077422, 2022).
Arthritis (3 papers, 2017 to 2025). Inflammation of a joint. "Loss of protein tyrosine phosphatase non-receptor type 2 amplifies the link between gut and joint inflammation through conversion of colonic Tregs into arthritogenic exTregs." (PMID 33055428, 2020). "We recently reported that Ptpn2 haploinsufficiency in SKG mice enhances the development of mannan-induced arthritis and causes increased accumulation of RORγt-expressing Tregs in arthritic ankles." (PMID 33055428, 2020). "In the present study we sought to understand how the interaction between loss of function of PTPN2 and intestinal inflammation affects the pathogenesis of arthritis in human carriers of IBD- and RA-associated PTPN2 variants." (PMID 33055428, 2020). "Despite these limitations, our study does support the idea that autoimmune-associated haploinsufficiency in Ptpn2 promotes development of arthritis through an action on a population of cTregs expressing GPR15." (PMID 33055428, 2020). "Arthritis in Ptpn2-haploinsufficient SKG mice is associated with accumulation of G protein–coupled receptor 15–positive CD4+ T cells." (PMID 33055428, 2020). "Our data validate the SKG model for studies at the interface between intestinal and joint inflammation and suggest that arthritogenic variants of PTPN2 amplify the link between gut inflammation and arthritis through conversion of colonic Tregs into exTregs." (PMID 33055428, 2020). "Ptpn2 haploinsufficiency in tamoxifen-inducible fate-mapping mice led to enhanced DSS-induced arthritis." (PMID 33055428, 2020). "Together, these results strongly suggest that increased arthritis development observed in mice receiving Ptpn2-haploinsufficient Tregs is due to selectively increased destabilization of GPR15+ Tregs." (PMID 33055428, 2020). "Overall, these results support the idea that Ptpn2 haploinsufficiency enhances DSS-induced arthritis in SKG mice by inducing a Treg-intrinsic reduction in cTreg stability, which is mainly restricted to GPR15+ cells." (PMID 33055428, 2020). "Th17 cells, total Tregs, and RORγt-expressing Tregs were also more expanded in the joints and lymph nodes of Ptpn2-haploinsufficient SKG mice with established arthritis." (PMID 33055428, 2020). "We next evaluated the number of total GPR15+ Tregs, GPR15+RORγt+FoxP3–CD4+ T cells, and GPR15+ RORγt-expressing Tregs in WT versus Ptpn2-haploinsufficient SKG mice subjected to mannan-induced arthritis." (PMID 33055428, 2020). "We next assessed the effect of tamoxifen-inducible Treg-selective haploinsufficiency of Ptpn2 in the context of DSS-induced arthritis." (PMID 33055428, 2020). "Mice receiving Ptpn2-haploinsufficient cTregs developed significantly more arthritis when compared with mice transferred with WT cTregs." (PMID 33055428, 2020). "DSS-induced arthritis was overall milder in male mice, consistent with previous observations that male SKG mice develop less severe arthritis and that Ptpn2 haploinsufficiency enhances arthritis less efficiently in male mice." (PMID 33055428, 2020). "We also leveraged the SKG model to demonstrate that partial loss of function of PTPN2, mimicking common genetic PTPN2 variations associated with both RA and IBD, in Tregs, interacts with gut inflammation to promote severity of arthritis." (PMID 33055428, 2020). "To gather further evidence that promotion of cTregs’ conversion into IL-17+ T cells contributes to the observed enhancement of DSS-induced SKG arthritis by Ptpn2 haploinsufficiency, we bred Ptpn2fl/+ SKG mice with a tamoxifen-inducible Treg fate-mapping model." (PMID 33055428, 2020). "Overall, the data suggest that Ptpn2 haploinsufficiency links colonic inflammation to arthritis triggering or severity via local induction of arthritogenic colonic T cells or peripheral expansion of such cells once they have circulated to arthritic joints." (PMID 33055428, 2020).
Arthritis (continued). "Increased colonic inflammation induced by 0.5% DSS correlated with dramatically enhanced arthritis development in Ptpn2-haploinsufficient SKG mice, with increased signs of synovial inflammation, bone erosion, and cartilage depletion at 28 days after DSS water." (PMID 33055428, 2020). "Ptpn2-haploinsufficient mice with early arthritis displayed a significant expansion of Th17 cells and RORγt-expressing Tregs only in arthritic ankles but not lymph nodes." (PMID 33055428, 2020). "Tamoxifen-induced Ptpn2 haploinsufficiency in these mice enhanced mannan-induced arthritis similar to that previously reported in the constitutive fate-mapping Ptpn2-haploinsufficient mice." (PMID 33055428, 2020). "The marked accumulation of GPR15+ exTregs in the joints and lymph nodes of Ptpn2+/– fate-mapping mice after low-dose DSS treatment suggests that cTregs’ instability at least in part links subclinical colonic inflammation to enhanced arthritis in these mice." (PMID 33055428, 2020). "Together, these results suggest that cTregs could be an important source of pathogenic IL-17+ exTregs in arthritic SKG mice and that cTreg destabilization can mediate enhanced arthritis development in Ptpn2-haploinsufficient SKG mice." (PMID 33055428, 2020). "Thus, it is possible that gut dysbiosis also contributes to enhancing arthritis severity in Ptpn2-haploinsufficient SKG mice." (PMID 33055428, 2020). "We recently showed that Ptpn2 haploinsufficiency, which models the loss of PTPN2 expression observed in carriers of PTPN2 risk alleles for IBD and RA, enhances development of Th17-dependent arthritis when introduced onto the SKG mouse background." (PMID 33055428, 2020). "Ptpn2 haploinsufficiency enhances SKG arthritis induced by subclinical colonic inflammation." (PMID 33055428, 2020). "To further characterize the role of PTPN2 in the stability of resident cTregs and determine whether there is a relationship between destabilization of cTregs and enhanced arthritis in Ptpn2-haploinsufficient mice, we focused on Tregs expressing G protein–coupled receptor 15 (GPR15)." (PMID 33055428, 2020). "Next, we sought evidence that the selective effect of PTPN2 on the stability of GPR15+ Tregs occurs in vivo and mediates the effect of Ptpn2 haploinsufficiency on SKG arthritis." (PMID 33055428, 2020). "Next, we cotransferred cTregs from either Ptpn2-haploinsufficient or WT CD45.2-marked FoxP3EGFP SKG mice in combination with CD4+ effector T cells isolated from CD45.1-marked WT SKG mice and evaluated the development of arthritis after mannan injection." (PMID 33055428, 2020). "During mannan-induced arthritis, there were increased numbers of both GPR15+ RORγt-expressing Tregs and RORγt+FoxP3–CD4+ T cells but not of total GPR15+ Tregs in both popliteal lymph nodes and ankles of Ptpn2-haploinsufficient SKG mice." (PMID 33055428, 2020). "However, when the colonic immunophenotype of Ptpn2-haploinsufficient mice was compared with WT mice, the only significant difference was a mild increase in total and CD4+ T cells in Ptpn2+/– mice with established DSS-induced arthritis." (PMID 33055428, 2020). "There was no other difference between Ptpn2+/– and WT mice in total and CD4+ T cells, cTh17 cells, total cTregs, or RORγt-expressing cTregs in early or late DSS-induced arthritis." (PMID 33055428, 2020).